ITGB3 (integrin subunit beta 3)
Diseases named in the same sentence as ITGB3 in open-access papers (continued):
Sharing a sentence is not in itself a finding about the gene and the disease.
osteosarcoma (continued). "Importantly, this study not only implicates ITGB3 as a candidate target for osteosarcoma radiosensitization but also highlights the positive role of osteogenic differentiation in inducing radiosensitivity." (PMID 40410897, 2025). "With respect to ITGB3 specifically, despite previous studies showing that it confers resistance to cisplatin in osteosarcoma and demonstrating the tumor-suppressing impact of ITGB3-KD, the role of ITGB3 in the radiosensitization of malignancies remains largely unexplored." (PMID 40410897, 2025). "Furthermore, the decreased osteosarcoma cell proliferation and migration ability in ITGB3 knockout osteosarcoma cells were related to increased apoptosis and slowing cell cycle progression." (PMID 36772869, 2023). "Collectively, these results indicated that ITGB3 promotes osteosarcoma cell proliferation in vitro." (PMID 36772869, 2023). "To study whether ITGB3 can affect osteosarcoma cisplatin resistance in vivo, we subcutaneously injected ITGB3‐KO and 143B cells into NOD/SCID mice (day 0)." (PMID 36772869, 2023). "Accordingly, these analyses suggested that ITGB3 may perform the functions of cisplatin resistance in osteosarcoma through these signaling pathways." (PMID 36772869, 2023). "Finally, we further explored the molecular mechanism of ITGB3 in the progression and recurrence of osteosarcoma." (PMID 36772869, 2023). "Finally, the molecular mechanism of ITGB3 in the progression and recurrence of osteosarcoma were explored via transcriptome analysis." (PMID 36772869, 2023). "The expression of ITGB3 was analysis in collected human osteosarcoma tissues." (PMID 36772869, 2023). "Taken together, our data showed that ITGB3 may be a critical regulator of cisplatin resistance in osteosarcoma." (PMID 36772869, 2023). "In addition, the potential functions of ITGB3 in the cisplatin resistance of osteosarcoma cells were investigated in vitro and in tumor xenotransplantation." (PMID 36772869, 2023). "Furthermore, the decreased osteosarcoma cell proliferation and migration ability in ITGB3 knockout osteosarcoma cells were also confirmed." (PMID 36772869, 2023). "However, further validation is needed to determine whether the increased osteogenic differentiation in osteosarcoma cells resulting from ITGB3-KD-mediated activation of the JNK/c-JUN/RUNX2 pathway directly regulates apoptosis in osteosarcoma cells." (PMID 40410897, 2025). "However, the relationship between ITGB3 expression and clinical prognosis and recurrence in osteosarcoma remains unclear." (PMID 36772869, 2023). "We demonstrated that the knockdown of ITGB3 increased radiosensitization by promoting osteogenic differentiation and apoptosis through activation of the JNK/c-JUN/RUNX2 pathway in osteosarcoma." (PMID 40410897, 2025). "To systematically validate this radiosensitization effect, we employed lentiviral transfection to establish long-term ITGB3-KD and ITGB3-NC HOS and U2OS osteosarcoma cell models." (PMID 40410897, 2025). "Based on siRNA transfection, short-term ITGB3-knockdown (ITGB3-KD) and ITGB3-negative control (ITGB3-NC) HOS and U2OS osteosarcoma cells were constructed, and the effectiveness of ITGB3 protein knockdown was verified by western blotting." (PMID 40410897, 2025). "To further validate the potential functions of ITGB3 on osteosarcoma cell growth and migration in vitro, we used the CRISPR/Cas9‐mediated disruption system to generate the ITGB3‐knockout 143B cell line." (PMID 36772869, 2023). "Next, through Cytoscape and STRING analysis of cisplatin‐treated or nontreated WT and ITGB3‐KO cell‐related RNA‐Seq data, we found that ITGB3 plays a role in promoting osteosarcoma progression through multiple signaling pathways." (PMID 36772869, 2023). "Intriguingly, our findings revealed that even in the absence of ITGB3-KD, augmenting osteogenic differentiation in osteosarcoma cells could elicit a radiosensitizing effect." (PMID 40410897, 2025).
osteosarcoma (continued). "To further determine whether the enhancement of osteogenic differentiation mediates a proapoptotic radiosensitizing effect in osteosarcoma, we used osteogenic differentiation medium (ODM) to cultivate ITGB3-KD and ITGB3-NC HOS cells for 10 days to promote osteogenic differentiation." (PMID 40410897, 2025).
acute coronary syndrome (5 papers, 2007 to 2024). Signs and symptoms related to acute ischemia of the myocardium secondary to coronary artery disease. "ITGB3 and ITGA2B as platelet glycoprotein IIb of IIb/IIIa which has already been used as therapeutic target to block platelet aggregation in acute coronary syndrome." (PMID 31534454, 2019).
acute myeloid leukemia (5 papers, 2021 to 2023). Acute myeloid leukemia (AML) is a group of neoplasms arising from precursor cells committed to the myeloid cell-line differentiation. "Through an shRNA screen, an involvement of both ITGAV and ITGB3 was demonstrated in leukemogenesis using MLL-AF9 acute myeloid leukemia (AML) model." (PMID 36204266, 2022).
bladder cancer (5 papers, 2016 to 2024). "The downregulation of Itgb3 through the action of MIR-320a is also associated with bladder carcinoma invasion in bladder transitional cell carcinomas." (PMID 35167594, 2022). "Notably, miR-320a was found to be downregulated in bladder cancer cells, and it was proposed to function as a tumor suppressor by targeting the integrin subunit beta 3 gene (ITGB3) and inhibiting cell invasion." (PMID 38846969, 2024).
metastatic melanoma (5 papers, 2018 to 2024). A melanoma that has spread from its primary site to another anatomic site. "Here we show that downregulation of ADAR1 in metastatic melanoma cells causes an increase in ITGB3 expression through RNA-editing-independent transcriptional and post-transcriptional mechanisms, leading to an increase in invasion rate." (PMID 29855470, 2018). "Consistent with its role in metastatic melanoma, ITGB3 is amongst the highest expressed genes in melanoma and, ITGA10, is highly expressed particularly in endothelial cells." (PMID 34439879, 2021). "In conclusion, it is suggested that targeting integrins and TGF-β signalling, specifically ITGA5, ITGB3, PAI1, and p21, may offer promising approaches to overcoming vemurafenib resistance, thereby improving outcomes for metastatic melanoma patients." (PMID 39063187, 2024). "The acquisition of the integrin αVβ3 (ITGB3) for example, is seen exclusively on metastatic melanoma but not on benign naevi." (PMID 34439879, 2021). "In metastatic melanoma, RNA editing-incompetent ADAR1 is able to negatively regulate the expression of the metastatic enhancer integrin beta-3 (ITGB3) by (i) inhibiting the transcriptional activator of ITGB3, PAX6, and (ii) promoting FOXD1-mediated induction of miR22 to block ITGB3 translation." (PMID 30619092, 2018). "Remarkably, analysis of ITGB3 and ADAR1 expression levels in 38 low-passage patient-derived metastatic melanoma cultures shows a highly significant negative correlation." (PMID 29855470, 2018).
autism spectrum disorder (4 papers, 2017 to 2022). A spectrum of developmental disorders that includes autism, and Asperger syndrome. "Several mutations in integrin β3 (Itgb3) or loci containing Itgb3 appear to be associated with autism spectrum disorder." (PMID 35247972, 2022). "We chose integrin β3 (Itgb3) for our study because a substantial body of literature associates Itgb3 as a quantitative trait locus for autism spectrum disorder and intellectual disability." (PMID 33317577, 2020). "Integrin subunits have been implicated in dendritic development, and the subunit with the strongest associations with autism spectrum disorder and intellectual disability is integrin β3 (Itgb3)." (PMID 33317577, 2020). "The integrin subunit that may be most closely associated with autism spectrum disorder is Itgb3, and comorbidities of Itgb3 variants may include echolalia and attention deficit hyperactivity disorder." (PMID 35247972, 2022). "Together, these findings strengthen the idea that Itgb3 has a specific role in shaping forebrain circuitry that is relevant to endophenotypes of autism spectrum disorder." (PMID 35247972, 2022). "Itgb3-knockout mice exhibit altered social and repetitive behavior, e.g., behavior relevant for autism spectrum disorder." (PMID 29163031, 2017). "Additionally, prior behavioral studies on mice with Itgb3 loss-of-function have not explicitly included females, even though women with certain Itgb3 mutations may be at an increased risk of autism spectrum disorder." (PMID 35247972, 2022).
cutaneous melanoma (4 papers, 2019 to 2024). A primary melanoma arising from atypical melanocytes in the skin. "Our findings are illustrated by two (DNAm-correlated) isoform switches we detected in tumor suppressor genes: BLHLE41 (in BLCA) and ITGB3 (in skin cutaneous melanoma, or 'SKCM')." (PMID 31329578, 2019).
depression (4 papers, 2016 to 2020). "Indeed, cell adhesion proteins, including those coded by CHL1 and ITGB3, were shown to play key roles in neurogenesis and synaptogenesis, which in turn, are crucial for remission from depression." (PMID 29163031, 2017). "Thus, it has been suggested that ITGB3 may play a key role in depression and remission of the disease." (PMID 31125682, 2019). "Moreover, single-nucleotide polymorphisms in neuronal cell adhesion genes involved in synaptic plasticity and identified in the two latter studies performed with human LCLs, namely, CHL1 and ITGB3, were recently shown to affect treatment response in depressive disorders." (PMID 27845776, 2016).
lung adenocarcinoma (4 papers, 2016 to 2023). A carcinoma that arises from the lung and is characterized by the presence of malignant glandular epithelial cells. "RNA data from the database TCGA showed that mRNA expression of ITGAV and ITGB3 correlated positively with SPP1 expression in lung adenocarcinoma and squamous patients." (PMID 33287873, 2020). "The lung adenocarcinoma patients were divided into two subgroups, ITGB3-high and ITGB3-low, based on their median expression level of ITGB3." (PMID 27015122, 2016).
Miscarriage (4 papers, 2019 to 2025). A pregnancy that ends at a stage in which the fetus is incapable of surviving on its own, defined as the spontaneous loss of a fetus before the 22th week of pregnancy. "In the embryonic chorion tissue of spontaneous abortion (SA), the expressions of H19 and ITGB3 at both the mRNA and protein levels decreased." (PMID 30780128, 2019). "Moreover, downregulation of ITGB3 was found in the secretory-phase endometrium of subjects with recurrent miscarriages and might have affected the early stage of embryo–endometrial interaction." (PMID 30780128, 2019).
psoriasis (4 papers, 2019 to 2024). An autoimmune condition characterized by red, well-delineated plaques with silvery scales that are usually on the extensor surfaces and scalp. "Increased ITGB3 expression has been reported in T helper 17‒associated skin inflammatory diseases such as psoriasis and psoriatic arthritis." (PMID 36699197, 2022).
autoimmune disease (3 papers, 2021 to 2026). A disorder resulting from loss of function or tissue destruction of an organ or multiple organs, arising from humoral or cellular immune responses of the individual to their own tissue constituents. "Moreover, ITGB3, a gene known to participate in cell adhesion and multidirectional regulation of anoikis, displayed significant upregulation in the tubular compartment in most of the renal diseases and was downregulated in the glomeruli of patients with autoimmune diseases SLE and IgA." (PMID 40072109, 2025). "The non-CHD indications of clinically used drugs included dyslipidemias (PPARA), type 2 diabetes (PPARG and NDUFA13), autoimmune diseases (TNF), neoplasms (RAF1 and PSMA5), circulatory disorders (ABCA1, PLG, ITGB3, and F2), and alcohol-dependency (ALDH2)." (PMID 34675202, 2021).
bone metastasis (3 papers, 2016 to 2022). Transfer of a neoplasm from its primary site to bones. "Finally, multivariate analysis including the panel of five CTC-biomarkers in combination with the presence of bone metastasis resulted in GAPDH, NOTCH1 and PTP4A3 as independent predictors of PFS; GAPDH and ITGB3 showed predictive value for OS." (PMID 27901069, 2016). "This study identified 74 DEGs between BRCA samples with or without bone metastasis, and 5 important DEGs were finally filtered, namely, MMP9, ITGB3, BMP2, CCL2, and PROM1." (PMID 36193308, 2022).
fibrosis (3 papers, 2021 to 2023). the formation of excess fibrous connective tissue in an organ or tissue in a reparative or reactive process. "By retracing the interaction between macrophages and HSC, we found that Thbs1 was derived from macrophages in the fibrosis model, and communicated with HSCs by interacting with the aVb3 (Itgb3) and a2Bb3 (Itga2b&Itgb3) complex receptors." (PMID 37724132, 2023). "As shown by Masson trichrome staining and SA-β-gal, F4/80, and Fn1 staining of mouse renal tissues, delivery of Itgb3-expressing plasmid significantly promoted the tubulointerstitial fibrosis, the infiltration of inflammatory cells, and cellular senescence after UUO." (PMID 34805144, 2021).
medulloblastoma (3 papers, 2015 to 2023). A malignant, invasive embryonal neoplasm arising from the cerebellum. "The restricted integrin-αvβ3 expression found in medulloblastoma-derived samples was corroborated in medulloblastoma cell lines, where only two of five exhibited ITGB3 overexpression." (PMID 38009896, 2023). "Compared to the normal cerebellum, the expression level of miR-192 in medulloblastoma cells is lower, and studies indicated that miR-192 suppresses the expressions of ITGAV, ITGB1, ITGB3, and CD47 in medulloblastoma." (PMID 35464451, 2022). "After miR-192 transfection, there was a significant reduction in ITGAV, ITGB1, ITGB3, and CD47 in all miR-192-transfected medulloblastoma cells in comparison with NC miR-transfected cells (all P values <0.05)." (PMID 26506238, 2015). "In summary, this study revealed that the loss of miR-192 expression exerts wide ranging effects on cell proliferation and cell anchoring by activating DHFR and by molecular cross talk between ITGAV, ITGB1, ITGB3, and CD47 in the leptomeningeal dissemination of medulloblastoma." (PMID 26506238, 2015).
multiple myeloma (3 papers, 2014 to 2023). "ITGB3 encodes integrin subunit beta 3, which was found to mediate the bone-resorbing function of osteoclast-like myeloma cells." (PMID 36897488, 2023). "RNA-sequencing analysis suggested communication between RUNX2, M-CSF, ITGB3, CD44, LCN2, and CLU in RUNX2 k/in myeloma cells." (PMID 36897488, 2023). "We aimed to investigate the relationship among epidermal growth factor–like protein-7 (EGFL7), integrin subunit beta 3 (ITGB3), and Kruppel-like factor 2 (KLF2) expressions and their clinical implication in multiple myeloma (MM)." (PMID 34635968, 2022).
non-small cell lung carcinoma (3 papers, 2014 to 2024). A group of at least three distinct histological types of lung cancer, including non-small cell squamous cell carcinoma, adenocarcinoma, and large cell carcinoma. "Down-regulated hsa-let-7c was significantly associated with metastasis and poor survival of patients, and hsa-let-7c inhibits cancer metastasis by degrading ITGB3 and MAP4K3 in non-small cell lung cancer." (PMID 26933913, 2016).
osteoporosis (3 papers, 2024 to 2025). A condition of reduced bone mass, with decreased cortical thickness and a decrease in the number and size of the trabeculae of cancellous bone (but normal chemical composition), resulting in increased fracture incidence. "Identifying 8 key genes as potential regulatory target genes for the differentiation of mesenchymal stem cells into osteoblasts or adipocytes under the condition of disuse osteoporosis (ITGB3, LAMC1, COL6A3, ITGA8, PDGFRB, ITGA4, LAMB1, LAMA4)." (PMID 40130165, 2025). "In an experiment using bone marrow mesenchymal stem cells (BMSC) in patients with osteoporosis (OP), the outflow of the miR-25–3p/ITGB3 axis was examined." (PMID 38892426, 2024). "It has also been shown that miR-25-3p targets ITGB3, which leads to the inhibition of osteogenic differentiation of bone marrow stem cells in patients with osteoporosis." (PMID 38892426, 2024). "In BMSCs isolated from osteoporosis patients, circPVT1 expression was negatively and positively correlated with miR-30d-5p and its target Integrin beta-3 (ITGB3), respectively." (PMID 38164139, 2024).
ovarian tumor (3 papers, 2009 to 2024). "The correlation of HRG/NRG1 and ITGB3 expression might be relevant to study in ovarian tumours as well, or there might be other unknown factors that regulate the impact of ITGB3 as a biomarker." (PMID 19775429, 2009). "GSE133859 provided paired OC samples, which demonstrated that ITGB3, ITGB4, ITGB7, and ITGB8 increased in ovarian tumor tissue compared with normal tissue." (PMID 38814534, 2024).
pneumonia (3 papers, 2014 to 2025). An acute, acute and chronic, or chronic inflammation focally or diffusely affecting the lung parenchyma, caused by an infection in one or both of the lungs (by bacteria, viruses, fungi, or mycoplasma.). "We measured the levels of four DEmRNAs (F13A1, ITGB3, ITGA2B and VWF) involved in platelet aggregation during SARS-CoV-2 infection in 5 patients with pneumonia and 6 normal donors by RT-qPCR." (PMID 35139909, 2022).
triple-negative breast carcinoma (3 papers, 2020 to 2022). An invasive breast carcinoma which is negative for expression of estrogen receptor (ER), progesterone receptor (PR), and human epidermal growth factor receptor 2 (HER2). "Preclinical studies have found that overexpression of ITGB3 facilitates cancer invasion and metastasis in HCC 36 and ALK-rearranged NSCLC 37, whereas ITGB3 silencing significantly inhibits EMT and metastasis of triple-negative breast cancer." (PMID 33456563, 2021).
virus infection (3 papers, 2020 to 2023). "RT-qPCR revealed that the relative mRNA level of ITGB3 increased after virus infection." (PMID 36706154, 2023).
adenomyosis (2 papers, 2022 to 2023). The growth of endometrial tissue inside the muscular wall of the uterine corpus. "The endometrial receptivity marker HOXA10 and its downstream target molecule ITGB3 were both decreased in the adenomyosis mouse model as well as during the secretory phase in patients with adenomyosis." (PMID 35937844, 2022).
Alzheimer disease (2 papers, 2021 to 2023). A progressive, neurodegenerative disease characterized by loss of function and death of nerve cells in several areas of the brain leading to loss of cognitive function such as memory and language. "Ten DEGs, including IGF1, VEGFC, RAPGEF3, PIK3CA, Akt3, ITGB3, ITGA11, SPP1, NOS1, and ATP6V0B, were selected from Rap1, oxidative phosphorylation, and Alzheimer’s disease signaling pathways." (PMID 34359260, 2021).
arterial hypertension (2 papers, 2024 to 2025). "This study investigates the association of ITGA2 (C807T) and ITGB3 (T1565C) gene polymorphisms with platelet characteristics in Azerbaijani patients with arterial hypertension (AH), focusing on potential thrombotic risk." (PMID 41346645, 2025). "Aim of the study: To study the distribution of polymorphic variants of integrin ITGA2 (C807T), ITGB3 (T1565C) and the association of genotypes with platelet characteristics in individuals with arterial hypertension in Azerbaijan." (PMID 41346645, 2025).